TNF (tumor necrosis factor)
Diseases named in the same sentence as TNF in open-access papers (continued):
Sharing a sentence is not in itself a finding about the gene and the disease.
cancer (continued). "Elevated levels of TNF-α are associated with numerous diseases, such as rheumatoid arthritis, inflammatory bowel disease, and cancer." (PMID 39830670, 2024). "IL-6, TNF-α, and IL-8 from CAFs influence adipose tissue loss, organ fibrosis, and appetite reduction, associated with cancer wasting and cachexia." (PMID 39676864, 2024). "Eventually, AG and GC rs361525 genotypes of TNFA gene polymorphism predicted higher serum TNFα and simultaneously a higher frequency of cancer." (PMID 38051374, 2024). "According to KEGG and GSEA analyses, UBR1 was significantly associated with several cancer pathways, oxidative phosphorylation, and the TNF-NFκB pathway." (PMID 39181686, 2024). "Inflammation is believed to increase the risk of PCa, and Tumor necrosis factor (TNF) plays an important role in the inflammatory process, which promotes the development of PCa by promoting the release of cancer-derived soluble factors." (PMID 39061044, 2024). "Tumor necrosis factor α (TNF-α) is known to be associated with chronic inflammation, and its expression has been shown to increase in advanced cancers." (PMID 38595736, 2024). "On the contrary, there is evidence suggesting that high TNF-α levels are associated with harmful effects such as cancer cell growth, invasion, and metastasis." (PMID 38776022, 2024). "Increased inflammatory cytokines in cancer cachexia, such as interleukin (IL)-1β, IL-6, and Tumor Necrosis Factor-α (TNF-α), cause lipid degradation and reduced lipid synthesis." (PMID 39272951, 2024). "Cancer treatments cause injury to the epithelial cells of the oral mucosa, leading to activation of factors such as TNF-α and IL-6, which are pro-inflammatory." (PMID 39456414, 2024). "TNF, or tumor necrosis factor, is an important pro-inflammatory cytokine implicated in the occurrence and progression of human cancer." (PMID 39342122, 2024). "The precise role of TNF in cancer is not fully understood, but it seems to be associated with its varying concentrations at different stages of tumorigenesis." (PMID 38339076, 2024). "Tumor necrosis factor-alpha has been implicated in cancer through its association with chronic inflammation, leading to numerous studies on this topic." (PMID 39830670, 2024). "M1 ATMs release TNF-α and IL-6, which not only contribute to insulin resistance but are also associated with cancer recurrence." (PMID 39064705, 2024). "The major pro-inflammatory cytokines include IL-1β, IL-6, and TNF-α, the continuous intensification of inflammation is an important cause of cancer." (PMID 38572238, 2024). "Intriguingly, the loss of TRAF2 sensitizes cancer cells to checkpoint inhibition, indicating that lowering the threshold for TNF cytotoxicity augments T-cell mediated killing." (PMID 38184997, 2024). "Decreased TNF-α levels/Increased the relative abundance of Paracoides/Down-regulated three genes (Hmgcs2, Fabp2, and Gpt) associated with inflammation and cancer." (PMID 39712006, 2024). "In this study, we aimed to identify the upstream mechanism activating TNF‐α, a cytokine that plays a complex role in predisposing the liver to chronic inflammation and the development of cancer." (PMID 38558505, 2024). "As a common pro-inflammatory factor in granulation tissue, TNF-α can cause EMT in several types of cancer cells and epithelial cells." (PMID 38515079, 2024). "B7-H3–high tumors in most cancer types displayed positive enrichment of Hallmark inflammatory response gene sets, Hallmark IFNγ response gene sets, Hallmark TNFα response gene sets, and Hallmark IFNα response gene sets." (PMID 38709075, 2024). "At the intersection of cancer and hematopoiesis, TNFα has been implicated in inducing myelopoiesis in the context of cancer." (PMID 38443597, 2024).
cancer (continued). "NK cells are the essential components of innate immunity that can release cytotoxic granules, such as perforin and granzymes to destroy cancer cells, or can cause cancer cell apoptosis through the production of TNF-α, FasL, and TRAIL genes." (PMID 36109471, 2023). "Inflammation and cancer appear to be linked, and TNF-α appears to be a key intermediary in that relationship." (PMID 36978464, 2023). "Overexpression of TNF is a prevalent hallmark in various cancers, emphasizing the need to determine if this discovery is exclusive to PDAC or a consistent phenomenon spanning a wide array of malignancies." (PMID 37455286, 2023). "As a result, the deregulation of TNF- Alpha production has been linked to several human illnesses, including cancer." (PMID 37214337, 2023). "The pan-cancer model identified NFκB/TNF hallmark genes implicated in multiple cancer types, as evidenced by their high prevalence across different cancer types and their corresponding high average votes." (PMID 37475016, 2023). "We also observed several downregulated cancer-related pathways and hallmark signatures, such as “Sana TNF Signaling Up” (33 genes, NES = − 2.65, FDR = 3.19E−5); however, the “DNA Repair” signature was upregulated (NES = 1.80, FDR = 4.91E−2)." (PMID 37012431, 2023). "TNF-α has been linked to several human cancers, including breast, gastric, pancreatic, ovarian, endometrial, prostate, bladder, colorectal, oral, and liver." (PMID 36980727, 2023). "Controlling for other potential predictors, individuals with SOT/HSCT had 55% [HR:1.55 (95% CI: 1.15, 2.10)] and PID/SID had 121% [HR: 2.21 (95% CI: 1.70, 2.86)] higher risk of cancer compared to recipients of TNF-i therapy." (PMID 36624408, 2023). "In CRC, M1 TAMs exert anti-cancer effects by secreting pro-inflammatory cytokines such as TNF-α and IL-1, and increased densities of M1 TAMs are linked with a favorable clinical outcome." (PMID 36693898, 2023). "Our proposed method demonstrated high accuracy in identifying NFκB/TNF hallmark genes in 13 out of 16 cancer types (AUC ≥ 0.75) and performed even better in the pan-cancer model (AUC = 0.94)." (PMID 37475016, 2023). "Patients with CD have a 2.4-fold increased risk of colorectal cancer, and those with IBDs treated with anti TNF-α Abs are at risk of developing cancer." (PMID 37185713, 2023). "The tumor necrosis factor (TNF) cytokine is a driver of inflammation and has been implicated in the development of cancer." (PMID 37809067, 2023). "For instance, FADD, FASLG, RIPK1, RIPK3, and TNF were more prone to copy number gain than loss in pan-cancer, but FAS and TLR3 displayed the reverse tendency." (PMID 37351504, 2023). "Several immune-related pathways were found to be significantly associated with high SERPINE1 expression in most cancers, including TNF-α signaling via NF-κβ, INF-γ response, and inflammation response." (PMID 37680718, 2023). "TNF-α drives cells into apoptosis at high doses and promotes their survival at low doses, but accumulation of mutations can shift this balance and make cancer cells less susceptible to apoptosis." (PMID 37555952, 2023). "The risk of malignant tumor progression has been a concern associated with the use of anti-tumor necrosis factor-alpha monoclonal antibody (anti-TNFα mAb)." (PMID 36996146, 2023). "Serum levels of IL-6, TNF-α, and other inflammatory and cancer-associated cytokines, as well as WBC, NEU, and CRP values, have a certain correlation with the development and progression of GLM; thus, they can reflect the disease to a certain extent." (PMID 37817809, 2023). "Inflammatory cytokines such as IFN-gamma, IL-1b, IL-2, IL-4, IL-6, IL-10, IL-12p70, and TNF-alpha have been shown to be involved in the immune response associated with cancer progression." (PMID 37373957, 2023).
cancer (continued). "Our study shows that common pro-inflammatory and SASP-associated factors, TNFα and IL-6, were both significantly reduced by sirolimus treatment in both normal and early cancer, which confirms a role of mTOR signaling in promoting the secretion of SASP factors." (PMID 37904250, 2023). "These tumors also had increased infiltration of Th17 cells, and previous literature linked IL-17 to PD-L1 expression in other cancer cells either alone or synergistically with IFN-γ/TNF-α." (PMID 36239683, 2023). "Depletion of FAP-expressing cells in lung and pancreatic carcinomas in mouse tumors causes rapid hypoxic necrosis of cancer and stromal cells in these immunogenic tumors, mediated by interferon-γ and TNFα." (PMID 37046676, 2023). "Nonetheless, this is also supported by our finding on RA indications, which is the only subgroup confirming the slightly increased risk of cancer in patients undergoing tofacitinib vs. anti-TNF." (PMID 37190126, 2023). "It was found that TNF-α was the link between inflammation and cancer and appears to be a critical mediator in this association." (PMID 37375312, 2023). "In this study, we identified several significant pathways linked to cancer progressions such as cancer proteoglycans, TNF signalling pathway, ovarian infertility genes, diseases of signal transduction, focal adhesion, and notch signalling pathway." (PMID 36608061, 2023). "It is well established that tumor necrosis factor (TNF) plays an instrumental role in orchestrating the metabolic disorders associated with late stages of cancers." (PMID 37294765, 2023). "As SM, NTG induces TNFα-dependent cancer cell death by apoptosis due to the loss of cIAP1 E3 ligase activity by a distinct molecular mechanism." (PMID 37173331, 2023). "A multi-provincial Canadian population-based study aims to investigate the association between anti-TNF and thiopurine therapies and cancer risks in the IBD population." (PMID 37674502, 2023). "Given the extensive use of TNF inhibitors for patients with AS, it is essential to continue monitoring the long-term risk profile for cancer in future studies." (PMID 37568555, 2023). "In this context, the newly identified candidate genes refer to those non-NFκB/TNF hallmark genes that received at least one vote across all cancer types, hereafter referred to as ‘candidates’." (PMID 37475016, 2023). "In our analysis of real-world data of 13,887 individuals, the risk of cancer was significantly higher in patients with PID/SID or SOT/HSCT relative to patients who received TNF-i therapy while controlling for other predictors of cancer risk." (PMID 36624408, 2023). "Our finding of a slightly higher risk of cancer (excluding NMSC) in patients who took tofacitinib than in those treated with anti-TNF agents should be interpreted with caution." (PMID 37190126, 2023). "Inflammatory mediators, including tumor necrosis factor-alpha (TNF-α), interleukin-6 (IL-6), and interleukin-10 (IL-10), have been implicated in cancer metastasis." (PMID 38116560, 2023). "In contrast, we found only a slightly higher risk of cancer in patients treated with tofacitinib compared with the patients treated with drugs that inhibit the tumor necrosis factor." (PMID 37190126, 2023). "Preliminary results from a safety clinical trial demonstrated an increased risk of serious heart-related diseases and cancer with tofacitinib compared to TNF inhibitors." (PMID 36986565, 2023). "The final results showed that the risk of MACE and cancer was relatively higher for the combined doses of tofacitinib (3.4% and 4.2%, respectively) than for the TNF inhibitor (2.5% and 2.9%)." (PMID 38138551, 2023).
cancer (continued). "Using the KEGG database, we identified several androgen-regulated pathways that are affected by both AR and HIRA KO, including cancer- and metastasis-associated pathways, as FoxO, TNF, TGF-beta, PI3K-Akt, MAPK and Wnt." (PMID 37638746, 2023). "While TNFα has long been implicated as an anti-cancer agent, it has been difficult to utilize for treatment since with systemic therapy there is near universal treatment related toxicity and opposing downstream effects which promote resistance." (PMID 36831373, 2023). "It is important to note that the accurate risk of cancer associated with anti-TNF is difficult to determine." (PMID 36983432, 2023). "Controlling for other potential predictors, individuals with SOT/HSCT had 57% [HR:1.57 (95% CI: 1.16, 2.13)] and PID/SID had 114% [HR: 2.14 (95% CI: 1.65, 2.77)] higher risk of cancer compared to recipients of TNF-i therapy." (PMID 36624408, 2023). "Inflammation has arisen as a viable cause both in CV disease and cancer, because correlation between tumour biomarkers and proinflammatory cytokines, such as TNF-α, IL-6 and IL-10, has been identified." (PMID 36830690, 2023). "The occurrence of cancer-related muscle loss is profoundly influenced by cytokine-mediated inflammation, specifically involving TNF-α, interleukin-1 (IL-1), IL-6, and interferon-gamma (IFNγ)." (PMID 37959329, 2023). "Several inflammatory mediators, such as tumor necrosis factor-alpha, interleukin (IL)-6, and IL-10, have been linked to cancer initiation and progression." (PMID 36836114, 2023). "Among the 23 NFκB/TNF hallmark genes voted in all 16 cancer types, EGR1, JUNB, and ZNF36 exhibited an average vote of 1,000." (PMID 37475016, 2023). "In a clinical trial with 86 patients with various types of solid tumors, patients with cancer cachexia benefited from additional melatonin supplementation compared to supportive care alone for three months to reduce TNF-α serum levels and weight loss." (PMID 37571328, 2023). "Being licensed more recently than anti-TNF agents, data on the risk for incident cancer induced by vedolizumab are sparse." (PMID 36831424, 2023). "Other reports have also identified TNFα signaling in metastasis in a variety of cancers, identifying perturbations associated with enhanced metastatic potential." (PMID 36980717, 2023). "Cytokines such as TNF-α and IL-8 have been implicated in cancer growth in both solid and hematological malignancies with studies showing their elevated levels in patients." (PMID 37232720, 2023). "Among the non-NFκB/TNF hallmark genes that received votes across all 16 cancer types, four genes (SRGN, CCN2, TNFRSF12A, and ZFP36L1) with an average vote exceeding 900 have been reported as regulated by TNF and NFκB." (PMID 37475016, 2023). "Curcumin also exhibited anti‐cancer properties against inflammation‐associated carcinogenesis by inhibiting TNF‐α mediated NF‐κB activation and inhibiting the proteasomal activity of IκB kinase in MCF‐7 cells." (PMID 37132286, 2023). "In this study, we trained an ensemble learning model on the transcriptome profiles from 16 cancer types in the TCGA database to identify a robust set of genes that are consistently associated with the NFκB/TNF pathway in cancer." (PMID 37475016, 2023). "Inflammatory factors can modulate the response of cancerous cells to chemotherapy, and anti-cancer drugs can cause the expression of some of the cytokine genes, including those of TNFα, IL-1β, and IL-6." (PMID 36834426, 2023). "Tnfaip2 has been reported to be associated with cancers and inflammation, which can be induced by tumor necrosis factor alpha (TNFα)." (PMID 37980507, 2023). "EMT is believed to maintain the stemness properties of cancer cells, whereas inflammation is a critical component and a hallmark of cancer, as many cancers are triggered from inflammation sites by cytokines released and mediated via the TNF-α pathway." (PMID 37958747, 2023).
cancer (continued). "TNFi and non-TNFα biologics exhibit similar safety profiles, with a generally low risk of cancer progression and recurrence." (PMID 37568640, 2023). "For example, IL-6, IL-1β, and TNF-α were increased at cancer early stage and associated with disease severity." (PMID 36899319, 2023). "Since inflammation is associated with the development and progression of cancer, inflammatory biomarkers such as pro-inflammatory cytokines, tumor necrosis factor (TNF), interleukins 1 and 6, and chemokines can be used to monitor cancer progression." (PMID 36836894, 2023). "Combined with the TNBC analysis, the findings from the LUAD patients reinforce the capability of our ensemble model in identifying patients with specific cancer types associated with the NFκB/TNF-regulated pathways." (PMID 37475016, 2023). "Tumor necrosis factor alpha (TNF-α) is one of the inflammatory cytokines involved in inflammatory signaling pathways and is linked to malignant tumor progression." (PMID 36829966, 2023). "EndMT is known to be initiated by TGFB1, and is exacerbated by TNF in cancer-associated fibroblasts; therefore, it is possible that the increases in content of TNF and TGFB1 during luteal regression can contribute to EndMT." (PMID 37841308, 2023). "TNF-α gene polymorphisms have also been associated with an increased risk for both oral pre-cancer and cancer development." (PMID 36980727, 2023). "Increased cytokines (such as TNF-α and IL-1) are believed to hastened cancer cachexia, with the symptoms of weight loss, anorexia, tiredness, and anemia." (PMID 37641070, 2023). "Most reports demonstrate a critical role for TNF-α in the two leading causes of death, cancers and cardiovascular diseases, despite medical progress and public awareness of protection." (PMID 36967438, 2023). "RIPK1 has been implicated in TNF-induced cell death and proposed as a target for cancer therapy to induce cancer cell death." (PMID 37090690, 2023). "Conversely, the overall cancer risk was slightly higher in patients who had taken tofacitinib vs. anti-TNF agents (RR 1.43; 95% CI 1.03–2.04; I2 = 0.00%; p = 0.03)." (PMID 37190126, 2023). "Specifically, our model takes the NFκB/TNF hallmark genes as positive samples and employs cancer patients as features to learn the transcriptomics pattern of NFκB/TNF hallmark across cancer patients." (PMID 37475016, 2023). "A Korean study of 191978 patients treated with either an IL-12/23 inhibitor or a TNF-α inhibitor examined the risk of cancers." (PMID 38139369, 2023). "Among the top 20 pathways, the TNF signaling pathway with a lower p-value was found to have a high association with carcinoma and was selected for subsequent validation." (PMID 37950195, 2023). "In hospitalized cancer patients with high grade DAEs, elevated elafin, IL-6, and TNF-α were shown to be associated with higher all-cause mortality." (PMID 35770005, 2022). "Lymphocytes, which can release cytokines such as interferon−γ and tumor necrosis factor−alpha (TNF−α), can improve the prognosis by causing apoptosis, suppressing cancer cell proliferation, invasion, and migration." (PMID 36061883, 2022). "The anti-inflammatory effects of TNF inhibitors have been suggested to play a role in reducing cancer risk since chronic inflammation has been implicated in the pathogenesis of cancer." (PMID 35945635, 2022). "Briefly, BAs on the one hand stimulate/reduce the secretion of inflammatory factors such as IL-6 and TNF-α, thereby activating/inactivating signaling pathways associated with cancer promotion to improve/inhibit cancer growth or invasiveness." (PMID 36338764, 2022). "Saliva cytokine levels of IL-1β, IL-2, IL-6 and TNF are not only associated with oral inflammation but also with the severity of oral mucosal damage in cancer patients." (PMID 35844493, 2022). "Pathways associated with these two groups were related to TNF signaling, sphingolipid signaling, cancer, MAPK signaling, Hippo signaling and dopaminergic synapse." (PMID 35464356, 2022).